MTOR (mechanistic target of rapamycin kinase)
Diseases named in the same sentence as MTOR in open-access papers (continued):
Sharing a sentence is not in itself a finding about the gene and the disease.
Insulin resistance (continued). "Particularly high levels of circulating amino acids and increased fat have been shown to contribute to nutritional overload, which boosts mTOR activation and can trigger insulin resistance in peripheral insulin-responsive tissues." (PMID 37762060, 2023). "Elevated BCAA can activate the mechanistic target of rapamycin (mTOR) complex 1/ribosomal protein S6 Kinase pathway, which leads to insulin resistance or to a build-up of metabolites that affect the pancreatic islet β-cells." (PMID 36681701, 2023). "Insulin resistance has been demonstrated in AD brain, and chronic mTOR activation has been proposed to contribute to insulin resistance." (PMID 37457922, 2023). "Previous studies have shown that the mTOR signaling pathway, insulin resistance, and FoxO signaling pathway are related to the occurrence of IUGR." (PMID 37510277, 2023). "The mTOR signaling pathway has a crucial role in regulating metabolic processes in various organs, including hepatic lipid metabolism, insulin resistance, chronic liver inflammation, and, ultimately, the advancement of NAFLD." (PMID 37760534, 2023). "One study showed that adipocyte-specific mTOR knockout mice had decreased adipose tissue mass and insulin resistance, further elucidating a relationship between mTOR and obesity." (PMID 37626871, 2023). "While DCM also displayed a similar enrichment of metabolic pathways, the regulation of the cellular metabolism via MTOR, MAPK, and FOXO signaling, as well as associated ‘insulin resistance’ and ‘glycolysis’ suggests differences in underlying pathogenesis." (PMID 37233155, 2023). "Insulin resistance or impaired insulin sensitivity is typical in AD and can be developed by activation of the mTOR (mammalian target of rapamycin)." (PMID 37597078, 2023). "In particular, insulin resistance, Wnt signaling, mTOR pathway, TGF-beta signaling, focal adhesion, MAPK, and PI3K-Akt signaling pathways are strongly associated with steatosis and hepatic fibrosis." (PMID 37111380, 2023). "Increased fat and elevated circulating amino acids in particular have been found to contribute to nutrient overload, which in turn increases mTOR activation which can result in insulin resistance in peripheral insulin-responsive tissues." (PMID 36826001, 2023). "Particularly, increased BCAA levels induce insulin resistance through activation of mTOR-IRS signaling and BCAA metabolite-induced oxidative stress." (PMID 37960324, 2023). "Illustrating reduced insulin resistance, oral simufilam improved the response to insulin of mammalian target of rapamycin (mTOR) and suppressed mTOR’s basal overactivation in lymphocytes of AD subjects." (PMID 37762230, 2023). "Treatment with sitagliptin ameliorated body weight gain, lipid metabolic disorder, and steatosis as well as hepatic insulin resistance in leptin-deficient ob/ob mice by inhibiting inflammatory responses and activating autophagy through the AMPK/mTOR pathway." (PMID 37739179, 2023). "Sustained activation of mTOR in AD also disables its activation by insulin, contributing to insulin resistance." (PMID 37457922, 2023). "Modulation of SIRT1/AMPK and Akt/mTOR pathways is crucial in reducing insulin levels, insulin resistance, glucotoxicity and lipotoxicity, and in increasing ketogenesis." (PMID 37152929, 2023). "In humans, the mTOR pathway is related to ovarian diseases such as polycystic ovarian syndrome, which exhibits insulin resistance due to excessive stimulation of the mTOR pathway." (PMID 37325555, 2023). "In conclusion, recent studies suggest that endogenous BCAAs, BCAA metabolism and mTOR-related autophagy play important roles in the relationships among BCAAs, longevity, and insulin resistance." (PMID 37408986, 2023). "The mTOR pathway can be promoted by positive energy imbalance, insulin resistance, and elevated insulin-like growth factors (IGFs)." (PMID 35608730, 2022).
Insulin resistance (continued). "Several serine/threonine kinases including JNK, mTOR, and p70 S6K cause serine phosphorylation of the insulin receptor substrate (IRS) and have been implicated in insulin resistance." (PMID 35011728, 2022). "Insulin signaling through the PI3K/AKT/mTOR pathways is considered to have an important role in insulin resistance." (PMID 35409099, 2022). "The tumor–host interaction causes insulin resistance and inhibit the myocardial protein synthesis pathway IGF‐1–PI3K–Akt–MTOR." (PMID 36105371, 2022). "In PCOS skeletal muscles, insulin resistance is attributed to the activation of mTOR that attenuates autophagy." (PMID 36523600, 2022). "Inhibition of AKT protein leads to inactivation of AKT/mTOR signaling, which in turn leads to insulin resistance and muscle atrophy in mice." (PMID 36105371, 2022). "Blockade of central ghrelin receptor can treat NAFLD possibly via the hypothalamic PI3K/Akt/mTOR signaling pathway to improve insulin resistance." (PMID 36246070, 2022). "A previous study found that insulin resistance results from the activation of mTOR that attenuates autophagy in PCOS skeletal muscles." (PMID 36523600, 2022). "Like muscle tissue, insulin resistance can also increase fat consumption by inhibiting the PI3K/AKT/mTOR pathway in adipose tissue." (PMID 36105371, 2022). "According to recent investigations, there are the following three possibilities to explain these benefits: anti-inflammatory effects, reduction of insulin resistance and increased activation of the mTOR pathway." (PMID 35889801, 2022). "Obesity and nutrient oversupply increase mammalian target of rapamycin (mTOR) signaling in multiple cell types and organs, contributing to the onset of insulin resistance and complications of metabolic disease." (PMID 36586433, 2022). "Our study showed that CSE ablation in skeletal muscle led to glucose intolerance and insulin resistance, which was associated with decreased GLUT4 protein levels and imbalances in PKG-1, IRS/PI3K/Akt, and mTOR/S6K/S6 signaling pathways." (PMID 36358588, 2022). "For the genes in the JAK-STAT signaling pathway, insulin resistance and mTOR signaling pathway shared at least two or more pathways." (PMID 36359184, 2022). "Altered signaling from growth factors, cytokines, and hormones are through MTOR and are involved in obesity and insulin resistance." (PMID 35937803, 2022). "In the presence of insulin resistance, activation of the mTOR pathway is inhibited and autophagy is activated." (PMID 36490255, 2022). "Increased mTOR activation in skeletal muscle of humans with obesity in the fasted state may result from effects of an obesity-associated insulin resistance on increasing the plasma amino acids, and given the role of increased concentrations of plasma amino acids (and insulin) in activating mTOR." (PMID 35350688, 2022). "On the other hand, HCV can induce insulin resistance by altering insulin signaling by alterations on the PI3K/Akt/mTOR pathways and the degradation of receptor substrate 1 (IRS-1)." (PMID 36560766, 2022). "A possible reason for these findings is that a defective BCAA catabolism regulates rapamycin (mTOR) pathway activation and insulin receptor substrate protein phosphorylation, which lead to insulin resistance and the accumulation of cytotoxic metabolites." (PMID 36014850, 2022). "When compared with untreated cells, we also found that DEX or TNF-α treatment of C2C12 cells induced insulin resistance, as demonstrated by the inactivation of mTOR, and reduced Dnmt1 expression and enhanced expression of miR-193b." (PMID 34913989, 2022). "We found that insulin resistance was the most significant enrichment pathway and was related to the mTOR, TNF, and MAPK pathways." (PMID 36077718, 2022). "EA was also reported to attenuate insulin resistance by inactivating the mTOR/4E-BP1 signaling pathway in a rat model of PCOS." (PMID 36353235, 2022).
Insulin resistance (continued). "As a matter of fact, the excessive activation of mTOR/S6K1 can induce cardiac insulin resistance, while the same pathway can also provide cardioprotection via increased angiotensin II (Ang II) type 2 receptor (AT2R) upregulation and adaptive hypertrophy." (PMID 35454166, 2022). "Deletion of DOCK5 in mice promoted obesity, insulin resistance, and altered glucose metabolism via activation of the mTOR/S6K1 pathway." (PMID 35682902, 2022). "In concordance with this context, in the current study, a positive correlation between mTOR and insulin resistance was found." (PMID 36476132, 2022). "Hyperactivation of mammalian target of rapamycin (mTOR) by nutrient excess has also emerged as a key factor in the development of insulin resistance." (PMID 35428325, 2022). "In a word, blockade of central ghrelin receptor can treat NAFLD possibly via the hypothalamic PI3K/Akt/mTOR signaling pathway to improve insulin resistance." (PMID 36246070, 2022). "The insulin resistance, subsequently, inhibited the phosphorylation of mTOR, a marker gene for protein synthesis." (PMID 34676967, 2021). "In the present study, alcohol intakes upregulated the miR-155-5p expression level, and the upregulation of miR155 should be protective to inactivate the mTOR signaling and ameliorate myocardial insulin resistance." (PMID 33868799, 2021). "This protective phenomenon is thought to result from the ability of AMPK to increase fatty acid oxidation, thereby decreasing fatty acid levels, or to inhibit mTOR signaling, as overactive mTOR is related to insulin resistance." (PMID 34831343, 2021). "The upregulation of the mTOR pathway is predominantly involved in this cardiac remodeling as a consequence of overfeeding and insulin resistance." (PMID 33716957, 2021). "There was a highly significant positive correlation between each of the following: LncRNA-RP11-773H22.4, RET, IGF1R, mTOR mRNAs, glycemic control and insulin resistance." (PMID 34360895, 2021). "It is conceivable based on our findings that miR-155-5p upregulation ameliorated ethanol induced myocardial insulin resistance via the mTOR signaling pathway." (PMID 33868799, 2021). "Alternatively, our data point to other potential disease mechanisms, including PA-mediated reduction in mTOR signaling promoting increased cell death, and glucosylceramide- and glycosphingolipid-mediated worsening of local insulin resistance and cell death." (PMID 34437304, 2021). "Insulin-induced protein proliferation and glucose- and amino acid-induced growth are dependent on mTOR signaling in pancreatic cells, as chronic mTOR activation results in insulin resistance characterized by hyperglycemia, and the onset of type 2 diabetes." (PMID 34069618, 2021). "Phosphatidylinositol 3-kinase (PI3K)/Akt signaling can downregulate autophagy by inhibiting the mTOR, and the changes in autophagy were associated with reduced PI3K/Akt signaling in insulin resistance." (PMID 34483960, 2021). "On the other hand when AMPK is inhibited, for instance in the palmitate model of insulin resistance, mTOR is stimulated." (PMID 34215308, 2021). "Hepatic SIRT1 deficiency in mice was shown to increase hyperglycemia, oxidative stress and insulin resistance through impaired AKT/mTOR signaling." (PMID 33806509, 2021). "Rapamycin has been shown to mitigate mTOR hyperactivity, even in a diet-induced insulin resistance scenario; furthermore, the induction of insulin resistance and mTOR hyperactivation exacerbate cognitive decline and AD pathogenesis." (PMID 34069890, 2021). "We aimed to explore the role of miR-155-5p up-regulation in chronic alcohol consumption induced myocardial insulin resistance and the mechanisms of mTOR signaling pathway involved in this process." (PMID 33868799, 2021). "It enhances lipid oxidation, suppresses de novo lipogenesis, and improves insulin resistance by inhibiting mammalian target of rapamycin (mTOR)." (PMID 33925827, 2021).
Insulin resistance (continued). "The role of systemic insulin resistance in modifying mTOR signaling in AD was recently probed using two rat models; ('T2DM': intraperitoneal streptozotocin (STZ) on high fat diet and 'AD': hippocampal Aβ injection)." (PMID 34215308, 2021). "Data so far collected indicate that dysregulation in insulin signaling pathway, insulin resistance in muscle and liver tissues and lipid accumulation occurs following aberrant up-regulation of mTOR signaling." (PMID 33615993, 2021). "A comparable β cell mass and a trend toward increase in insulin levels between the female mTOR-KOPlacenta and controls suggested insufficient compensation to combat insulin resistance present in the mTOR-KOPlacenta offspring." (PMID 34032632, 2021). "Direct genetic deletion of mTOR from the placental trophoblasts of mice conferred a significant reduction in newborn body weight that manifested in sexually dimorphic outcomes in insulin resistance and obesity in the adult offspring." (PMID 34828683, 2021). "Another study showed that elevated let-7 expression increased insulin resistance while inhibition of the let-7 reduced insulin resistance and improved glucose uptake in the diabetic myocardium through Akt and mTOR pathways." (PMID 34489723, 2021). "mTOR activation and insulin resistance in rats is increased with BCAA supplementation, but only when combined with a diet that was also high in fat." (PMID 33923531, 2021). "Two significant factors contributing to lipogenesis and insulin resistance are life-span determinant p66Shc (a 66 kDa proto-oncogene Src homologous-collagen homolog (Shc) adaptor protein) and the mTOR/S6K cascades." (PMID 33615993, 2021). "Abnormal mTOR activation enhances both Aβ deposition (by inhibiting clearance) and possibly generation (indirectly, via insulin resistance, insulinemia and hyperglycemia)." (PMID 34215308, 2021). "It is a consensus that brain insulin resistance in AD is promoted by a chronic mTOR signaling pathway hyperactivity, pointing to this metabolism master regulator as a critical target for therapeutic research." (PMID 34069890, 2021). "Thirdly, miR-155-5p overexpression protect against myocardial insulin resistance, accompanied by negatively regulated mTOR signaling pathway in alcohol-drinking rats." (PMID 33868799, 2021). "For instance, adipocyte-specific MTOR-silencing in mice led to insulin resistance and inhibited adipocyte differentiation via the peroxisome proliferator-activated receptor γ signaling pathway." (PMID 34573680, 2021). "Despite such limitations, our study clearly showed that miR-155-5p upregulation ameliorated myocardial insulin resistance via the mTOR signaling pathway." (PMID 33868799, 2021). "While adult female offspring with mTOR knockout in utero demonstrate high-fat diet-induced insulin resistance, they have normal beta-cell mass and function compared to littermate controls." (PMID 34828683, 2021). "miR-155-5p upregulation ameliorates myocardial insulin resistance via the mTOR signaling in chronic alcohol drinking rats." (PMID 33868799, 2021). "Organic zinc showed beneficial effects in the EV induced PCOS rats via decreased insulin resistance and mTOR expression, restored the hormonal profile, and decreased the number of cysts in the ovaries." (PMID 32405346, 2020). "To further identify the mechanism of CaMKIV on insulin resistance, we next analyzed the markers of ER stress, autophagy and insulin sensitivity after blockage mTOR/CREB signaling in Tun-treated adipocytes." (PMID 32660483, 2020). "On the other hand, due to an increase of the IGF-1/IGFBP-3 ratio, this stimulates the predominance of high mTOR-dependent metabolic activity and insulin resistance." (PMID 33333870, 2020). "This study was aimed to investigate the beneficial effects of organic Zn supplementation on insulin resistance, fertility, and mTOR gene expression as a novel component of polycystic ovary syndrome in PCOS rats." (PMID 32405346, 2020).
Insulin resistance (continued). "It has been noted that chronic activation of mTORC1, one of the mTOR protein complexes, contributes to obesity by enhancing excess fat accumulation in white adipose tissue, liver and muscle, which promotes insulin resistance." (PMID 32093387, 2020). "But long-term high-protein intake seems to result in insulin resistance in the whole body, by increasing mTOR/S6K1 signaling pathway and stimulating gluconeogenesis and high glucagon turnover." (PMID 33042976, 2020). "BCAAs can directly activate the mammalian target of rapamycin (mTOR) signaling pathway to induce insulin resistance, or function together with fatty acids." (PMID 33013697, 2020). "ZBPYR also reduced the deposition of Aβ in the mPFC, improved brain insulin resistance, and modulated the mTOR-autophagy pathway." (PMID 32372981, 2020). "Inhibition of the mTOR pathway results in glucose intolerance, insulin resistance, and downregulates glycolysis, leading to a reduction in ATP levels." (PMID 32127537, 2020). "mTOR had been identified as a new target for cancer therapy, which was found to be activated in many cellular processes, including insulin resistance, adipogenesis, tumor formation, angiogenesis, and lymphocyte activation." (PMID 32908897, 2020). "BCAAs were shown previously to be involved in several pathways of insulin resistance, including fatty acid oxidation, mTOR, JNK and IRS1 pathways." (PMID 32972433, 2020). "Inhibiting the expression and activity of mTOR can reduce insulin resistance and prevent glomerular hypertrophy, basement membrane thickening, and albuminuria." (PMID 31119177, 2019). "mTOR signaling modulates aging and age-related diseases while insulin resistance amplifies chronic inflammation leading to accelerated aging." (PMID 31316728, 2019). "The enriched KEGG pathways included the Autophagy-animal, mTOR signaling pathway, Apoptosis, and Insulin resistance, which were closely associated with the developments of the ovaries and follicles." (PMID 31221102, 2019). "Several mechanisms have been suggested, for example, it reduces insulin resistance and suppresses the mammalian target of rapamycin (mTOR) by activating the liver kinase B1 (LKB1) dependent adenosine 5′-monophosphate-activated protein kinase (AMPK) pathway." (PMID 31518336, 2019). "Our results show that cg08862778 (MTOR) is hypomethylated in older subjects and also, in those subjects who exhibit abdominal obesity, hypercholesterolemia, insulin-resistance and/or metabolic syndrome." (PMID 30926763, 2019). "Given that the IR/Akt/mTOR pathway is a determinant of insulin sensitivity, galangin and pinocembrin are likely to abrogate insulin resistance in hepatocytes through modulation of the IR/Akt/mTOR pathway." (PMID 31805752, 2019). "Obesity promotes mTOR activity in adipose tissue, leading to exacerbated hyperlipidemia and insulin resistance." (PMID 31130916, 2019). "It was initially thought that enhanced BCAA leads to activation of the mTOR/S6K1 kinase signaling pathway and phosphorylation of serine residues on IRS-1, which further cause insulin resistance." (PMID 31481892, 2019). "The mTOR pathway was activated in the liver and skeletal muscle of obese rats involved in obesity-induced insulin resistance." (PMID 31080547, 2019). "These particular amino acids are involved in the activation of the mammalian target of rapamycin (mTOR) and, therefore, the promotion of insulin resistance." (PMID 31717901, 2019). "Other immunosuppressives lead to different effects, with steroids inducing peripheral insulin resistance and impairing glucose uptake, the exact diabetogenic mechanism of mTOR inhibitors is still uncertain." (PMID 31035960, 2019). "Several studies indicated that berberine inhibits the mTOR pathway with abnormally high activity in the state of insulin resistance mainly by activating AMPK activity, so as to mediate the insulin signaling pathway and improve insulin resistance." (PMID 31915452, 2019).